S1PR1 (sphingosine-1-phosphate receptor 1)
Diseases named in the same sentence as S1PR1 in open-access papers (continued):
Sharing a sentence is not in itself a finding about the gene and the disease.
tumor (continued). "Further experiments indicated that ERO1α promoted tumor angiogenesis and positively correlated with VEGF-A expression via the S1PR1/STAT3/VEGF-A pathway, suggesting that ERO1α may be a novel therapeutic target for inhibiting tumor angiogenesis." (PMID 30377291, 2018). "DP T cells expressed ITGAE (codes for CD103), and CD69, but not SELL, KLF2, and S1PR1, suggesting a tumor resident phenotype." (PMID 30534127, 2018). "Previous studies reported that S1PR1, one of five G protein-coupled receptors for S1P, could maintain persistent STAT3 activation in tumorigenesis and is essential for tumor metastasis and angiogenesis." (PMID 30377291, 2018). "Memory T-cells in tumor tissue have been reported to be characterized by the absence of S1PR1, which may suggest that memory T-cells are able to remain in the location of tumor tissue for long periods of time by not being receptive to S1P signaling via S1PR1." (PMID 38542328, 2024). "However, S1P inhibited M1 macrophage-mediated phagocytosis of DLBCL tumor cells opsonized with the CD20 monoclonal antibodies rituximab and ofatumumab, an effect that could be reversed by an S1PR1 inhibitor." (PMID 38339325, 2024). "Interestingly, our viability and migration analyses showed that the pro-tumoral effect of THP-1 on GBM cells was not detectable when tumor cells were treated with the S1PR1 modulator ACT-209905 in parallel." (PMID 37686550, 2023). "The results showed that FB1 significantly promoted xenograft development regardless of whether EC S1PR1 was knocked down, indicating that the level of ceramide in tumour tissue affects tumour growth." (PMID 36068200, 2022). "In tumour samples from patients with melanoma and prostate cancer, the mechanism involves the activation of intrinsic STAT3 in B cells leading to the secretion of angiogenic factors S1PR1, MMP9, HIF1a, VEGF, and their accumulation around micro vessels in the tumour." (PMID 35350071, 2022). "Upon validation, primary tumor tissues from the MFBD mice exhibited significant increases in TNFα expression compared to tumors from the OOBD fed mice as well as increased an expression of S1PR1 and MMP9; however, these were not statistically significant." (PMID 34371939, 2021). "Given the negative correlation between S1PR1 expression and estimated tumor purity, we suggest that the proportion of normal tissue adulterated in tumor samples may also affect S1PR1 expression." (PMID 34503284, 2021). "Thus, the existence of the miR-363/S1PR1/ERK pathway may mostly explain the biological inhibition of proliferation, migration and invasion of tumour cells by miR-363 in ccRCC." (PMID 32536815, 2020). "In addition, S1PR1 levels were significantly negative with regard to the tumor purity of BRCA (r = − 0.508, P = 1.76e-66), LUAD (r = − 0.353, P = 6.05e-16), and LUSC (r = − 0.402, P = − 5.20e-20)." (PMID 32799825, 2020). "Thus, S1PR1 and S1PR2 may show opposing effects on tumor angiogenesis, making S1PR1 a potentially more interesting target when focusing on TAM." (PMID 31379883, 2019). "STAT3 is a transcription factor for S1PR1 and, simultaneously, enhanced S1PR1 expression activates STAT3 and upregulates IL-6 expression, a proinflammatory cytokine crucial for STAT3 activation and inflammatory cell-mediated transformation and tumor progression." (PMID 31534132, 2019). "After S1PR1 expression was significantly downregulated in HCT116, the proliferation, migration, and invasion capabilities were significantly decreased in vitro when compared with the control group and resulted in a significant decrease in subcutaneous tumor size and fewer liver metastases in vivo." (PMID 31534132, 2019). "Hence, we concluded a novel molecular mechanism in which ERO1α promoted the metastasis and angiogenesis of HCC through S1PR1/STAT3/VEGF-A signaling, suggesting that reagents targeting the pathway would be beneficial for inhibiting tumor metastasis and angiogenesis." (PMID 30377291, 2018).
tumor (continued). "Apparently, S1PR1 in CD11bhi CD206+ TAMs is a nonredundant mediator of tumor lymphangiogenesis." (PMID 28804221, 2017). "In addition, the FTY720 may have anti-cancer effects, so the reducing reduction of antibodies may be due to the decrease in tumor, rather than decreased S1PR1." (PMID 34484174, 2021). "Tumor tissues derived from AGSR cells, but not corresponding normal tissues of AGS cells, showed expression of CAGEs, MDR1, pBeclin1Ser15, S1PR1, and LC-3II." (PMID 38920983, 2024). "S1PR1 is critical in the regulation of inflammatory processes driving neovascularisation, providing tumours with the nutrients and oxygen needed for cancer cell survival, with S1PR2 and S1PR3 having some compensatory functions in the absence of S1PR1." (PMID 35158806, 2022). "We also found treatment with TCM derived from the MC38-exS1PR1 group induced strong S1PR1 and p-STAT3 activation in MDSCs without tumor cell challenge compared to the MC38-exControl group and untreated group." (PMID 31534132, 2019). "The inhibition of S1PR1 and S1PR3, but not S1PR2, could attenuate tumor angiogenesis and inhibit the expression of angiogenic factors." (PMID 35201458, 2021). "The absence of S1PR1 leads to Y1175 phosphorylation, a subsequent internalization of VEGFR2, ephemeral Rac1 activity, and strong ERK1 activity which results in ineffective tumor angiogenesis." (PMID 34690821, 2021).
cancer (124 papers, 2011 to 2026). A tumor composed of atypical neoplastic, often pleomorphic cells that invade other tissues. "Involvement of the signal transducer and activator of transcription 3 (STAT3), which is activated by the S1PR1 pathway in causing inflammation and cancer has also been explained." (PMID 34001212, 2021). "S1PR1 regulates different molecules in various types of cancer, of which the most important aspect is associated with angiogenesis." (PMID 30814488, 2019). "Moreover, an SPHK1-driven NF-κB/IL-6/STAT3/S1PR1 amplification loop, was also essential for the development and progression of colitis-associated cancer." (PMID 36361531, 2022). "Thus, S1P/S1PR1 signaling was shown to be closely linked to a persistent activation of STAT3 in cancer cells." (PMID 34289244, 2021). "Targeting the S1PR1-S1P axis or its downstream effectors offers a promising strategy to improve cancer immunotherapy outcomes." (PMID 41857410, 2026). "This structural combination allows the design of compounds capable of modulating key cancer-related targets such as S1PR1, CYP26A1, APN/CD13, and eEF2K, supporting the structure–activity relationship approach." (PMID 40807478, 2025). "Its partner mRNA S1PR1, involved in vasculogenesis and cancer cell motility via the RAC-CDC42 and ERK pathways, displayed reduced expression in the single-omics analysis." (PMID 40040391, 2025). "S1P was also found to be able to enhance cancer cell viability and promote cancer cell growth and metastasis by binding to S1PR1." (PMID 38794152, 2024). "A pivotal mechanism underlying this enhancement involves the activation of the STAT3 signaling pathway by S1PR1, thereby fostering cancer initiation, growth, and dissemination." (PMID 39551792, 2024). "Our work suggests that targeting the S1P/S1PR1 axis with FTY720 is a multipronged approach to bolster the anti‐cancer effects of paclitaxel in TNBC while concurrently mitigating CIPN." (PMID 39126272, 2024). "Specifically, S1P induces lymphatic endothelial cell tube formation in an S1PR1-dependent manner, and S1P is also involved in cancer-induced lymphangiogenesis." (PMID 38542328, 2024). "It is necessary to examine the role of S1PR1 for a better understanding of CAGE-promoted anti-cancer drug resistance." (PMID 38920983, 2024). "SMYD3 promotes S1PR1 expression by promoting histone methylation in the S1PR1 promoter region, thereby promoting the progression of malignant tumors." (PMID 36611207, 2023). "It has been demonstrated that FTY720 blocks the SPHK1/S1P/S1PR1 axis, leading to the blockade of the NF-kB/IL-6/STAT3 amplification loop and colitis-associated cancer." (PMID 36714534, 2023). "S1P activates its cognate receptors, including S1PR1-5, that regulate various physiological and pathological processes such as cardiovascular disease and cancer." (PMID 37828220, 2023). "It has also been shown that fingolimod mitigates cancer-induced bone pain and neuroinflammation in mice and alleviates bortezomib-induced neuropathic pain in rats by S1PR1 antagonism." (PMID 35250559, 2022). "Accordingly, further studies are required to address if systemic S1PR1 inhibition or rather cell type-specific blockade of S1PR1 would be beneficial for cancer patients." (PMID 35163211, 2022). "In cancer cells, signaling through S1PR1 leads to the activation of RAC1, SRC, PTK2/FAK1, as well as MAP kinases, and influences cell proliferation and survival in GBM." (PMID 34359681, 2021). "Overall, the downstream signaling pathways activated by S1P through S1PR1-5play central roles in regulating the cell proliferation, survival, migration, and invasion of cancer cells." (PMID 33920887, 2021). "Onco-suppressor factors, such as miR-125b-1-3p, downregulate the expression of S1PR1 to suppress the migration and invasion of cancer cells and induce apoptosis." (PMID 32545648, 2020).
cancer (continued). "SK1 produces the phospholipid S1P, which exerts its functions through intracellular actions or ligation to five cell surface G-protein-coupled receptors (named S1PR1-5) expressed both on cancer cells and cells of the TME38,39." (PMID 31974367, 2020). "In an inflammation-driven cancer setting, we previously reported that myeloid S1PR1 signaling induces IL-1β production by enhancing NLRP3 (NOD-, LRR- and Pyrin Domain-Containing Protein 3) inflammasome activity." (PMID 32630814, 2020). "It is well known that S1PR1 plays a crucial role in the development and progression of malignant tumours." (PMID 32536815, 2020). "These observed correlations between S1PR1 and the prognosis and immune cell infiltration provide a foundation for further research on its immunomodulatory role in cancer." (PMID 32799825, 2020). "S1PR1 is involved in multiple cellular processes, such as cell proliferation, migration, invasion, vascular maturation and angiogenesis, in many cancers." (PMID 32536815, 2020). "We systematically analyzed the expression levels of S1PR1 and the prognostic value in different types of cancers." (PMID 32799825, 2020). "S1PR1 can regulate many functions of cancer cells, including proliferation, survival, migration, morphogenesis and angiogenesis, by modulating various downstream genes." (PMID 32536815, 2020). "Herein, we used Oncomine, Kaplan-Meier plotter, PrognoScan, UALCAN and GEPIA datasets to analyze S1PR1 expression and its relationship with the prognosis of cancer patients." (PMID 32799825, 2020). "It has been reported that S1P/S1PR1 signaling pathway was involved in promoting cancer cell proliferation." (PMID 31438989, 2019). "S1PR1 has been reported to be engaged in the regulation of cancer growth, proliferation, and apoptosis." (PMID 31438989, 2019). "In our investigation, high S1PR1 expression was found to lead to reduced VE-cadherin expression in cancer cell membranes." (PMID 30814488, 2019). "In a transgenic mouse model of inflammation-driven cancer, we have previously shown that macrophage S1PR1 signaling is crucial for lymphangiogenesis by activating the NLRP3 inflammasome and subsequent activation of IL-1β release." (PMID 31357710, 2019). "Briefly, the signaling pathways activated by S1P through S1PR1–5 signaling play specific roles in regulating the proliferation, migration, and/or invasion of cancer cells in a context-dependent manner." (PMID 31807117, 2019). "S1P released by dying cancer cells also triggered HIF-1α accumulation in macrophages downstream of S1PR1, even under normoxic conditions." (PMID 31379883, 2019). "To better understand the molecular mechanism that S1PR1 regulates ESCC cancer cell apoptosis, we further examined the expression of proteins related to apoptosis." (PMID 31438989, 2019). "Previous studies have shown that S1PR1 can participate in the proliferation and invasion of cancer cells by activating the ERK signaling pathway." (PMID 30498398, 2018). "The essential nature of S1PR1 in normal cell physiology also adds to the difficulty of targeting this specific S1PR as a cancer therapy." (PMID 28869494, 2017). "In a CAC mouse model, treatment with FTY720 to block S1PR1 activation reduced both upregulations of S1PR1 and SphK1 in the carcinomas." (PMID 29333002, 2017). "For the most part, binding of S1PR1 has been shown to promote migration of several cancer cell lines, while S1PR2 exerted opposite effect." (PMID 27800303, 2016). "In this review, we discuss the recent advances of the role of the SphKs/S1P/S1PR1 axis in immunity and cancer." (PMID 27129720, 2016). "But most interestingly, the relevance of GPCRs in cancer drug discovery was revisited recently and the potential role of S1PR1 in particular highlighted." (PMID 22558171, 2012). "Further evidence suggests that endogenous aPC limits cancer cell extravasation and cancer cell-induced vascular leakage in a sphingosine-1-phosphate receptor-1 dependent manner." (PMID 21320357, 2011).
cancer (continued). "However, the specific receptors of S1P and subsequent events in a niche can be varied depending on cancer types for instance, in bone metastasis breast cancer, S1PR1 and IL-22R1 are up-regulated." (PMID 38419070, 2024). "Furthermore, the signaling of S1P via its receptor S1PR1 induces cancer cell survival by inducing anti-apoptotic pathways." (PMID 38419070, 2024). "We also examined the hypothesis that targeting the S1P/S1PR1 axis with FTY720 is a multi‐pronged approach to enhance the anti‐cancer effects of paclitaxel while suppressing CIPN." (PMID 39126272, 2024). "Furthermore, according to related research, S1PR1 regulates lymphocyte proliferation and differentiation inside the cancer microenvironment." (PMID 38794152, 2024). "Moreover, S1PR1, as a pro-tumorigenic factor, has been shown to activate cancer cell signaling pathways leading to invasion, migration, and proliferation." (PMID 35565311, 2022). "Intriguingly, S1PR1 has also been found on cancer cells, making it critical to investigate whether cancer cells can utilize the S1P gradient as a means of egress from lymph nodes in order to disseminate further." (PMID 33808959, 2021). "A previous study confirmed that S1PR1 is crucial for persistent STAT3 activation in cancer." (PMID 34059068, 2021). "Moreover, S1pr1, a novel promising target in cancer therapy, was broadly down-regulated across the five tissues examined in our study." (PMID 34209243, 2021). "We performed CCK8, colony formation, cell cycle, apoptosis, and transwell assays to explore whether SMYD3-mediated S1PR1 activity was involved in cancer cell development and progression." (PMID 34301921, 2021). "S1P can promote cancer cell viability, survival, growth, and transformation by activating S1PR1." (PMID 34503284, 2021). "Some studies have reported a critical role for S1PR1 in cancer biology." (PMID 34301921, 2021). "Accordingly, S1PR1 expression patterns depend on the type of cancer." (PMID 32799825, 2020). "In ER-positive breast cancer patients, high membrane S1PR1 expression was associated with shorter time to recurrence, whilst high cytoplasmic S1PR1 was correlated with shorter disease-specific survival times, suggesting a cancer promoting role of S1PR1 subtype." (PMID 31935914, 2020). "In addition, there are close and complex interactions among S1P, SphK, S1P transporter, its degrading enzymes, and S1PR1–5, and they all play important roles in cancer, inflammation, immune, and angiogenesis." (PMID 31807117, 2019). "In line with our previous study on the role of macrophage S1PR1 and inflammation-driven lymphangiogenesis in cancer models, we expected alterations in the onset and resolution phase of inflammation in this mouse model of IMQ-induced psoriasiform skin inflammation." (PMID 31357710, 2019). "Therefore, targeting S1PR1 affects inflammatory macrophage activation needs to be approached in a context-dependent manner, although it emerges as a promising target in cancer." (PMID 31379883, 2019). "The patients with tumors showing high STAT3 expression had a significantly higher risk of both disease progression (p = 0.009) and cancer-specific mortality (p = 0.009), but not with tumors expressing S1PR1 or IL-6." (PMID 30091994, 2018). "In this study, we found a cancer suppressive function of S1P through S1PR1." (PMID 29923327, 2018). "Those S1PR1 agonists could be candidates for the further investigation of the role of S1P/S1PR in cancer progression." (PMID 29923327, 2018).